LGALS9 (galectin 9)
Diseases named in the same sentence as LGALS9 in open-access papers (continued):
Sharing a sentence is not in itself a finding about the gene and the disease.
experimental autoimmune encephalomyelitis (4 papers, 2015 to 2024). An autoimmune demyelinating disease of the central nervous system that is produced experimentally in animals by the injection of homogenized brain or spinal cord in Freund's adjuvant. "Galectin-9 (Gal-9), the first ligand identified for TIM-3, eliminates interferon γ-producing Th1 cells, thereby reducing the severity and mortality of experimental autoimmune encephalomyelitis." (PMID 39650660, 2024).
head and neck carcinoma (4 papers, 2012 to 2024). A carcinoma that arises from the head and neck region. "Studies revealed enhanced expression level of LGALS1 in NPC-derived Tregs, which was reported to mediate immunosuppression by upregulation of cell-surface programmed death-ligand 1 (PD-L1) and galectin-9 (Gal-9) in head and neck cancer." (PMID 35311066, 2022). "Similarly, in absence of lactate, activation of NF-κB prevents the transcription of the IC Galectin-9 (Gal-9) by binding to histone deacetylase HDAC3 in head and neck carcinoma cell lines." (PMID 36713558, 2022).
kidney damage (4 papers, 2013 to 2025). "And one of TIM-3's main ligands, Galectin-9 on immune cells showed a decreasing trend in gene expression as kidney damage worsened." (PMID 38812511, 2024). "Lgals9 was primarily expressed on immune cells, endothelial cells, and fibroblasts, with a decreasing trend in gene expression as kidney damage worsened." (PMID 38812511, 2024). "Notably, mice lacking galectin-9 suffered significantly worse kidney damage." (PMID 40904455, 2025).
liver diseases (4 papers, 2010 to 2024). "Patients with biochemical evidence of highly active CHB-related liver disease (ALT>100 U/L) had significantly higher levels of serum galectin-9 than CHB patients with ALT<50 IU/L, (p = 0.01) or healthy controls (p = 0.02)." (PMID 23112829, 2012). "Galectin-9 has pleiotropic roles and may represent a novel therapeutic target in patients with viral or inflammatory diseases of the liver." (PMID 20209097, 2010). "Moreover, given the broad array of responses induced by galectin-9, including potentially detrimental processes, this pathway may be important in mediating immunopathology in other hepatic diseases." (PMID 20209097, 2010).
thyroid cancer (4 papers, 2017 to 2025). "Taken together, our results show that M2 macrophage markers and TIM3/galectin-9/CEACAM1 expression levels are increased in thyroid cancer tissues, thereby supporting our in vitro findings." (PMID 34638305, 2021).
allergic asthma (3 papers, 2017 to 2025). A asthma with a basis in a pathological type I hypersensitivity reaction. "Galectin-9 is evidenced to have both a pro-inflammatory and an anti-inflammatory role in allergic asthma." (PMID 40636105, 2025). "In models of allergic asthma in mice and guinea pigs, higher expression of galectin-9 in the lungs was related to an increase in the recruitment of eosinophils." (PMID 40636105, 2025). "More studies into the role of galectin-9 are however needed to determine whether similar mechanisms play a role in allergic asthma and whether HMOs could potentially influence galectin-9 levels in a similar fashion as GOS/lcFOS." (PMID 40636105, 2025).
chronic hepatitis C (3 papers, 2010 to 2018). "Using an ELISA test, we have detected unusually high concentrations of galectin-9 in the blood of patients with chronic hepatitis C, especially those HCV-related hepatocellular carcinomas." (PMID 22805533, 2012). "The fold induction of galectin-9 was higher in patients with chronic hepatitis C (7 fold) compared to normal controls (1.8 fold)." (PMID 20209097, 2010).
colorectal tumor (3 papers, 2018 to 2023). "In this study, we found that expression of ICs including PD-1, CTLA-4, TIM-3, TIGIT, and IC ligands including PD-L1 and galectin-9 was significantly higher in colorectal tumor tissues compared with normal tissues." (PMID 30081950, 2018). "We found that the expression levels of PD-1, CTLA-4, TIM-3, TIGIT, PD-L1, and galectin-9 were significantly higher in colorectal tumor tissues, compared with colon normal tissues." (PMID 30081950, 2018). "In the present study, we showed that galectin-9 expression levels in colonic polyps and non-polyp tissues were similar between WT and Clec7a−/− mice, suggesting that β-glucans in food rather than the endogenous ligand is involved in the Dectin-1-dependent regulation of colorectal tumor development." (PMID 36932082, 2023).
gastric tumor (3 papers, 2022 to 2025). "Our analysis revealed that both LGALS9 and HAVCR2 are upregulated in gastric tumors and associated with poor patient survival." (PMID 40666515, 2025). "The interaction between EP11-CLDN7 and CD8+ T cells was dominated by the interactions of LGALS9—HAVCR2 and HVEM—CD160 both of which are well-known checkpoints that inhibit CD8 + T cell functionality, suggesting an immunosuppressive function of the gastric tumor cells." (PMID 36550535, 2022).
latent infection (3 papers, 2019 to 2024). "We consider that the elevated levels of galectin-9 in the serum of active TB may be an indicator of the host immune response to Mtb infection, however, the magnitude of elevated galectin-9 is not sufficient to control Mtb infection and maintain latent infection." (PMID 39495223, 2024).
liver failure (3 papers, 2012 to 2024). A liver disease characterized by the liver losing or has lost all of its function. "Indeed, biochemical and histopathological data indicated that a single injection of galectin-9 was sufficient to protect against Con A–induced liver failure." (PMID 23118999, 2012).
Pleural effusion (3 papers, 2017 to 2025). The presence of an excessive amount of fluid in the pleural cavity. "Our previous research confirmed that molecules such as LGALS9, MIF, and RETN were significantly elevated in the MPE of LCP compared to the pleural effusion of HP." (PMID 40959273, 2025).
sarcoma (3 papers, 2013 to 2023). A usually aggressive malignant neoplasm of the soft tissue or bone. "For high LGALS9 expression, CESC, BRCA, bladder urothelial carcinoma (BLCA), HNSC, MESO, sarcoma (SARC), and SKCM showed worse prognostic probability, while having better patient outcomes for UVM, LGG, and KIRC." (PMID 36354714, 2022).
small cell lung carcinoma (3 papers, 2020 to 2025). Small cell lung cancer (SCLC) is a highly aggressive malignant neoplasm, accounting for 10-15% of lung cancer cases, characterized byrapid growth, and early metastasis. "A similar result was also described in small cell lung cancer, claiming that high galectin-9 expression on TILs indicated better LRFS in patients." (PMID 35145510, 2021).
acute alcoholic hepatitis (2 papers, 2019 to 2021). "T cells with an impaired function from patients with acute alcoholic hepatitis, showed higher levels of PD1 and PD-L1, or TIM3 and galectin-9, compared with that of T cells from controls." (PMID 31244862, 2019).
acute leukemia (2 papers, 2017 to 2022). A clonal (malignant) hematopoietic disorder with an acute onset, affecting the bone marrow and the peripheral blood. "Furthermore, plasma levels of galectin-9 were elevated as MDS progressed to the advanced stage in 70 MDS/acute leukemia transformed from MDS patients and was a prognostic factor in 40 MDS patients." (PMID 29179486, 2017).
anemia (2 papers, 2024). A reduction in the number of red blood cells, the amount of hemoglobin, and/or the volume of packed red blood cells. "Speaking of the association with anemia or thrombocytopenia and CD38 expressions, CLL patients with anemia and/or thrombocytopenia had significantly higher plasma levels of CXCL13 and galectin-9 than patients without these complications (p < 0.05, p < 0.0001, and p < 0.0001, respectively)." (PMID 37946029, 2024).
Behçet’s disease (2 papers, 2017 to 2024). "The administration of galectin-9 to mice with HSV-induced Behçet’s disease inhibits pro-inflammatory cytokine production, attenuates inflammation, and reduces disease severity; however, galectin-9 administration also increases the number of Tregs." (PMID 28991189, 2017).
bronchiectasis (2 papers, 2019 to 2024). Segmental, irreversible dilation of the bronchial tree resulting in the accumulation of secretions which leads to obstruction. "Here, we identified that serum levels of galectin-9 (Gal-9), a pleiotropic immunomodulatory protein, are elevated in RA patients, and are even further increased in patients with comorbid bronchiectasis, a lung disease caused by chronic inflammation." (PMID 31430907, 2019).
bullous pemphigoid (2 papers, 2023 to 2025). Bullous pemphigoid (BP) is the most common form of autoimmune bullous dermatosis. "In addition to galectin-10, the immunomodulator galectin-9 is also elevated in serum and in lesional skin samples of patients with bullous pemphigoid." (PMID 37509055, 2023).
Burkitt lymphoma (2 papers, 2012 to 2025). A rare form of malignant mature B-cell non-Hodgkin lymphoma. "No galectin-9 was detected in BL2 cells (EBV-negative human B-cells derived from an EBV-negative Burkitt’s lymphoma) in agreement with one of our previous report." (PMID 22805533, 2012).
chronic pancreatitis (2 papers, 2020 to 2025). A chronic inflammatory process causing damage and fibrosis of the pancreatic parenchyma. "Validation of galectin-4 and galectin-9 modulation at the protein level is also essential to confirm their potential as biomarkers or therapeutic targets in chronic pancreatitis." (PMID 41462636, 2025). "We analyzed circulating galectin-9 in healthy individuals (n = 28), patients with chronic pancreatitis (n = 18), intraductal papillary mucinous neoplasms (IPMN, n = 18), and PDAC (n = 70)." (PMID 32055023, 2020). "Furthermore, galectin-9 discriminated PDAC from chronic pancreatitis and IPMNs with c-statistics of 0.711 and 0.668, respectively." (PMID 32055023, 2020). "We next investigated, whether galectin-9 was able to discriminate PDAC from chronic pancreatitis, IPMN, and healthy normal controls." (PMID 32055023, 2020).
glomerulonephritis (2 papers, 2020 to 2025). A renal disorder characterized by damage in the glomeruli. "Correspondingly, we validated that serum galectin-9 levels were significantly higher in PMN group compared to other glomerulonephritis groups or HC." (PMID 40904455, 2025).
immune deficiency (2 papers, 2020 to 2024). "Taken together, these results further emphasized the significance of CD8+TILs exhaustion induced by TIM3/Galectin-9 pathway in the immune deficiency and tumor escape of DLBCL." (PMID 38369502, 2024). "In stark contrast to those of normal mice, in the background of immunodeficiency, the tumor growth rate and survival time of GL-261nSMase2−/−, Rab27a−/−, and LGALS9−/− tumor-bearing mice were not significantly different from those of GL-261WT tumor-bearing mice." (PMID 33093453, 2020).
intracerebral hemorrhage (2 papers, 2022). A cerebrovascular disorder characterized by bleeding into one or both cerebral hemispheres including the basal ganglia and the cerebral cortex. "In a model of intracerebral hemorrhage, a correlation was found between galectin-9 expression and the number of type 2 microglia, as well as an anti-inflammatory cytokine profile." (PMID 36008956, 2022).
myocarditis (2 papers, 2014 to 2022). Myocarditis is a condition that is characterized by inflammation of the heart muscle (myocardium). "The present studies were designed to investigate whether Tim-3/galectin-9 plays a role in murine acute myocarditis induced by CVB3 by manipulating the Tim-3/galectin-9 system in one or more cell types involved in causing myocarditis." (PMID 24573249, 2014). "We found that galectin-9 remarkably increased the frequencies of CD11b+Gr-1+ cells in the cardiac tissue and spleen with myocarditis." (PMID 24573249, 2014). "The objective of the study was to explore the effects of galectin-9 on myeloid suppressor cells in Coxsackievirus B3 (CVB3)-induced myocarditis and the possible mechanisms involved." (PMID 24573249, 2014). "Our previous study indicated that galectin-9 administration effectively ameliorates CVB3-induced myocarditis by promoting the proliferation of T regulatory cells and the activation of Th2 cells." (PMID 24573249, 2014). "Our results indicate that galectin-9 therapy may represent a useful approach to ameliorate CVB3-induced myocarditis." (PMID 24573249, 2014).
neuroblastoma (2 papers, 2023 to 2025). Neuroblastoma (NB) is the most common solid, extracranial childhood tumor. "In contrast, we did not observe the upregulation of LGALS9, a molecule involved in regulating T-cell death and proposed as a target for cancer immunotherapy in MYCN-A neuroblastoma." (PMID 39860532, 2025).
non-alcoholic fatty liver disease (2 papers, 2018 to 2024). "Even if galectin-9 can also stimulate natural killer cell proliferation by increasing TIM3+ Kupffer cells' secretion of IL-15, exogenous administration of galectin-9 decreases the development of nonalcoholic fatty liver disease." (PMID 29950926, 2018).
Opportunistic infection (2 papers, 2020 to 2021). An infection that is caused by a pathogen that would generally not be able to cause an infection in a host with a normal immune system. "Patients from VNR and failure groups are also more likely to suffer from opportunistic infections which might influence Galectin-9 levels." (PMID 32678033, 2020).
periodontitis (2 papers, 2023 to 2024). An acute or chronic inflammatory process that affects the tissues that surround and support the teeth. "In patients with periodontitis and patients with T2D and periodontitis, we observed that LRRC25+ IM exhibited normal intercellular communications with other cell clusters, mainly through LGALS9 associated signaling pathways." (PMID 39544234, 2024). "This study aimed to compare the salivary galectin-3 and galectin-9 levels in periodontitis, gingivitis, and periodontally healthy patients." (PMID 37809904, 2023). "The galectin-3 and galectin-9 levels were significantly higher in the periodontitis and gingivitis groups than in the healthy group (p < 0.001)." (PMID 37809904, 2023). "The salivary galectin-3 and galectin-9 levels were high in patients with periodontitis and gingivitis, suggesting that they could be potential biomarkers for periodontal diseases." (PMID 37809904, 2023).
refractory anemia (2 papers, 2017 to 2022). "Plasma galectin-9 levels in AL-MDS patients were significantly elevated in comparison with those in patients with refractory anemia (RA) and RAEB (P = 0.0051 and P = 0.0013, respectively)." (PMID 29179486, 2017).
acute T-cell lymphoblastic leukemia (1 paper, 2024). "The role of CD74 and COPA in regulating the immunosuppressive microenvironment as well as the function of LGALS9 and HAVCR2 in regulating T-cell responses signified that they may be potential targets for the treatment of acute T-cell lymphoblastic leukemia." (PMID 39422621, 2024).
astrocytoma (1 paper, 2025). "Comparison of the grade 3 astrocytoma to the matched normal sample, revealed the top three DEGs encoding ECM glycoproteins (NTN1, AEBP1 and SPARC) and ECM-affiliated factors (C1QA, LGALS9 and C1QL1)." (PMID 41366031, 2025).
bacteremia (1 paper, 2015). "Intriguingly, Gal-9-/- mice exhibited significantly lower bacterial counts in their blood at 2dpi than their WT counterparts at that time point indicating a delayed development of bacteremia in the absence of galectin-9." (PMID 25898318, 2015).
bone cancer (1 paper, 2022). A primary or metastatic malignant neoplasm affecting the bone or articular cartilage. "LGALS9, for example is a gene that produces Galactin-9, a well-studied protein expressed on tumour cells, and DMBT1 is a tumour suppressor gene involved in bone cancer that like IGF1R has been previously identified as key velvet antler peptide." (PMID 35151275, 2022).
carcinoid (1 paper, 2022). "In the GEO Database, we examined mRNA expression of the LGALS9 gene (which encodes Gal-9) in carcinoid, (n = 24), LCNEC (n = 56), and SCLC (n = 21) cases." (PMID 36263183, 2022).
Cerebral ischemia (1 paper, 2012). Restriction of arterial blood supply to the brain associated with insufficient oxygenation to support the metabolic requirements of the tissue. "We showed that the galectin-9/Tim-3 pathway is involved in neuronal injury induced by cerebral ischemia and that LRP attenuated the expression of galectin-9 and Tim-3 in the ischemic brain, suggesting that the inhibition of this pathway may contribute to the protective effects of LRP." (PMID 22347410, 2012).
chronic fatigue syndrome (1 paper, 2024). "This study aimed to assess plasma galectin-9 (Gal-9) and artemin (ARTN) concentrations as potential biomarkers to differentiate individuals with Long COVID (LC) patients with myalgic encephalomyelitis/chronic fatigue syndrome (ME/CFS) from SARS-CoV-2 recovered (R) and healthy controls (HCs)." (PMID 39386210, 2024).
chronic hepatitis (1 paper, 2024). An active inflammatory process affecting the liver for more than six months. "Similarly, HAVCR2 and LGALS9 expression of nMac in patients with chronic hepatitis overlapped in patients with HBeAg+ chronic infection." (PMID 39135698, 2024).
chronic liver failure (1 paper, 2024). Liver failure that develops slowly and gradually for some time, possibly for years, often as the result of cirrhosis, or malnutrition. "Galectin-9 (Gal-9) expression in patients with acute-on-chronic liver failure and its correlation with prognosis remain unclear." (PMID 39333198, 2024).
clear-cell renal cell carcinoma (1 paper, 2015). "The role of the different types of galectins seems to be tumor type dependent though, and galectin-9 has been correlated with poor survival in clear-cell renal cell carcinoma." (PMID 26066796, 2015).
colon adenocarcinoma (1 paper, 2024). "Notably, quantitative analysis demonstrated a modest yet statistically significant reduction in both ATXN3 and Galectin-9 in malignant colon adenocarcinoma compared to adjacent normal colon tissues." (PMID 38815863, 2024).
colon adenoma (1 paper, 2024). An adenoma that arises from the colon. "Intriguingly, a robust positive correlation between ATXN3 and Galectin-9 was observed in both colon adenomas and adenocarcinomas, as expected; however, this correlation was absent in adjacent healthy colon tissues." (PMID 38815863, 2024).
corneal disease (1 paper, 2026). "Namely, expression of LGALS9 (galectin-9) was upregulated in both keratoconus and the OA + keratoconus groups, indicating an involvement with immunomodulatory effects and corneal disease." (PMID 41596322, 2026).
cutaneous melanoma (1 paper, 2022). A primary melanoma arising from atypical melanocytes in the skin. "As in cutaneous melanoma, the anti-MAA clonotypes formed frequent inhibitory interactions with tumor cells via PVR – TIGIT/CD96 and with immune cells via Galectin 9 – TIM3." (PMID 36220826, 2022).
cystic fibrosis (1 paper, 2015). Autosomal recessive disorder caused by pathogenic variants in the CFTR gene (cystic fibrosis transmembrane conductance regulator), which encodes a chloride and bicarbonate channel expressed in epithelial cells, and follow the diagnosis criteria. "Galectin-9 has also been shown to induce IL-8 production by bronchial epithelial cells in cystic fibrosis, influencing neutrophil infiltration and early neutrophil-dominated inflammation in the cystic fibrosis lung." (PMID 25898318, 2015).
endometrial cancer (1 paper, 2024). Primary or metastatic malignant neoplasm involving the endometrium (mucous membrane that lines the endometrial cavity). "Cytosolic Galectin-8 expression is a positive prognostic factor for OS and PFS, while cytosolic presence of Galectin-9 in endometrial cancer is correlated to a better prognosis regarding overall survival." (PMID 39000016, 2024).